MMP2 (matrix metallopeptidase 2)
Diseases named in the same sentence as MMP2 in open-access papers (continued):
Sharing a sentence is not in itself a finding about the gene and the disease.
tumor (continued). "Our data also showed that TFPI-2 counteracts tumor invasion by negatively regulating MMP-2 activation, consistent with the finding that TFPI-2 is associated mainly with the inhibition of ECM degradation." (PMID 25179542, 2014). "In conclusion, our study demonstrates that POU5F1 and MMP-2 contribute to tumor invasion and migration phenotype of LACSLCs, and aberrantly high expression of POU5F1 can enhance MMP-2 expression by directly targeting the promoter of MMP-2." (PMID 24386189, 2013). "MMP-2 acts in multiple ways on tumor cells by modulation of their metabolism, their receptor turnover, and their resistance to apoptosis." (PMID 24023566, 2013). "The final anti-tumor effects were measured by the tumor volume and weight as well as the intratumoral activity of MMP2 and MMP9." (PMID 24304581, 2013). "The knock-down of B7-H3 lead to matrix metalloproteinase (MMP)-2, another tumor prognostic marker cell reduced in cell level." (PMID 23947693, 2013). "In this study, to our knowledge, we demonstrate for the first time that GRN163L treatment decreases the migration/invasive capacity of tumor cells, possibly through the downregulation of MMP-2." (PMID 23545855, 2013). "Co-localization of αvβ3 and MMP-2 was first observed on angiogenic blood vessels and at the tumor invasive front." (PMID 24194929, 2013). "MMP-2 promotes tumor vascularization and, in turn, renders the tumor cells resistant to radiotherapy." (PMID 23381805, 2013). "Rat neurological signs, survival time, tumor size, hematoxylin and eosin (HE) staining and immunohistochemical staining for MMP-2, MMP-9 and β-catenin were compared." (PMID 23946812, 2013). "Then, we down-regulated Capn4 expression in ICC cell lines with specific small interfering RNA (siRNA) to assess the role of Capn4 in tumor cell migration, invasion and proliferation, and matrix metalloproteinase 2 (MMP2) expression." (PMID 23349941, 2013). "Because of its ability to degrade the basement membrane, MMP-2 has been postulated to be a potential marker of tumor progression and prognosis." (PMID 23281640, 2013). "It has previously been reported that in NSCLC, the level of MMP-2 is increased in tumor cells, as well as in the peritumoral stromal tissues." (PMID 23545855, 2013). "Matrix metalloproteinases, especially MMP-2 and -9 play pivotal roles in tumor cell invasion and metastasis due to their ability to degrade type IV collagen, a major component of the ECM." (PMID 23563849, 2013). "Downstream target pathways of FOXM1 include vascular endothelial growth factor (VEGF), matrix metalloproteinase-2 (MMP-2), and β-catenin, each of which promotes tumor formation and progression." (PMID 23404835, 2013). "EGFR has been shown to be associated with tumor proliferation and growth, Bcl-2 inhibits tumor apoptosis and MMP-9 and MMP-2 play an indispensable role in tumor invasion and metastasis." (PMID 23420470, 2013). "There are many cytokines secreted by aHSCs that are associated with tumor invasion and metastasis, ingcluding HGF, EGF, IL-1, IL-2, IL-6, MMP-2, MMP-9, TGF-β, TNF-α, VEGF and Wnt families." (PMID 23622143, 2013). "Studies have shown that inhibiting MMP-2 activity reduces the metastatic potential of malignant cells and MMP-2 downregulation leads to decreased tumor cell invasion." (PMID 23314174, 2013). "With regard to MMPs, the relative expression level of MMP-2 in tissues of invasive ductal breast carcinomas was significantly higher than that of adjacent non-tumor tissues." (PMID 23457587, 2013). "The expression level of SATB1 showed correlation with tumor differentiation and pTNM stage, and SATB1 was also associated with the expression of various biologic markers (including Cyclin D1, MMP-2, NF-κB, PCNA, APC and BRAFV600E)." (PMID 23326301, 2013).
tumor (continued). "We also used web-driven software to identify potential gene targets of these key miRNAs and found that two of virtually predicted miRNA target genes, PIK3R1 and MMP-2, were promising anti-tumor targets in CCA cell signal pathways." (PMID 24147037, 2013). "Our data here implicates both MMP-2 and -9 secreted by astrocytes in the tumor invasion and metastasis process." (PMID 24324647, 2013). "Amongst others, YB-1 activates gene expression of the epidermal growth factor receptor (EGFR), matrix metalloproteinase 2 (MMP-2) and of the receptor tyrosine kinase c-MET, all this associated with tumor cell adhesion, invasion and metastasis." (PMID 24044901, 2013). "For more than 24 h exposure to hypoxia, these authors found an increase in expression of genes involved in tumor invasion, including matrix metalloproteinase 2 (MMP-2)." (PMID 24167746, 2013). "Owing to above results we concluded that tumor cells obtained migratory and invasive ability indicated by MMP2 and MMP9 stimulation, whereas ZEB1 required further elucidation in other ccRCC cell lines." (PMID 24023875, 2013). "In nude mice, siRNAs against MMP2 resulted in decreased tumor invasion, migration, and angiogenesis, with a 60% reduction in tumor size." (PMID 23621950, 2013). "These anti-tumor effects on OSCC are associated with the suppression of AKT and the repression of DNA-binding activities on MMP-2 and MMP-9 promoters." (PMID 23799155, 2013). "Further investigation revealed that the expression of ANXA2 in HCC cells affected the shedding of CD147-harboring membrane microvesicles, acting as a vehicle for CD147 in tumor-stromal interactions and thereby regulating the production of MMP-2 by fibroblasts." (PMID 23950866, 2013). "We also demonstrated that, similar to tumor invadopodia, MMP-2 preferentially functions in a localized region surrounding AF cells, rather than being secreted and acting at a distance." (PMID 23621950, 2013). "Hypoxia, macrophages, granulocytes and endothelial cells are known to activate MMP-2 in tumour invasion and angiogenesis but the specific mechanism of MMP-2 activation in vivo is yet not fully understood." (PMID 23641796, 2013). "IR-enhanced expression and activation of MMP-2 modifies tumor progression by altering the availability of various molecules that promote tumor angiogenesis." (PMID 23381805, 2013). "In present study, we analyzed the clinical significance of MMP-2 and B7-H3 expression in primary tumor samples resected from pancreatic cancer patients." (PMID 23947693, 2013). "Both peptide sequences were in turn linked by an octapeptide, cleavable by the MMP-2 (gelatinase A) and MMP-9 (gelatinase B) enzymes which are over expressed in tumor tissues, allowing the release of buforin IIb." (PMID 24101917, 2013). "This suggests that strong MMP-2 expression in the primary lesion contributes to the invasiveness of primary tumor cells, leading to metastases and poor survival outcomes." (PMID 24069584, 2013). "MMP2, a protein closely correlated with tumor cell migration, was detected using a western blot assay." (PMID 24223658, 2013). "MMPs, especially MMP-2 and -9 play key roles in tumor cell invasion and metastasis due to their ability to degrade type IV collagen, a major component of the ECM." (PMID 23563849, 2013). "MMP-2 is known to promote tumor invasion, remote metastasis, and angiogenesis by degrading components of the extracellular matrix, mainly type IV collagen." (PMID 24147037, 2013). "MMP-2 expression was enhanced with increased clinical stage and metastasis (P < 0.05), but was unrelated to patient age or tumor grade (P > 0.05)." (PMID 24245968, 2013). "MMP-2 was present in both tumor and stromal cells; however, MMP-9 was present in stromal, vascular and perivascular cells surrounding nests of tumor cells." (PMID 23446555, 2013). "Circadian variations of relative PER1 and MMP-2 mRNA expression, tumor growth and proliferation of tumor bearing mice of 4 time groups." (PMID 23405233, 2013).
tumor (continued). "Among which, tumor invasion factors namely matrix metalloprotease-2 (MMP-2) and MMP-9 were partly responsible for the astrocyte media-induced tumor cell invasion." (PMID 24324647, 2013). "And there results were opposite to that of MMP-2, which plays an important role in tumor cell invasion and metastasis." (PMID 23405233, 2013). "As well, MMP-2 is overexpressed in tumor tissues and activation of MMP-2 results in ECM degradation, which facilitates the invasion and metastasis of tumor cells." (PMID 24130681, 2013). "This was achieved via downregulation of promoters of angiogenesis (VEGF and IL-8) and invasion (MMP-2) together with decreased tumor blood vessel density (decreased CD31 staining)." (PMID 23533772, 2013). "Our findings that POU5F1 can positively regulate MMP-2 expression to promote tumor cell invasion and migration of LACSLCs have important clinical implications." (PMID 24386189, 2013). "ROS, MMP-2 and interleukin-6 (IL-6) can interact directly between tumour cell spheroids and endothelial cell monolayer." (PMID 23516489, 2013). "Meanwhile, the VEGF, pVEGFR-2 and MMP2 expression were also significantly down-regulated in ISL treated tumor samples." (PMID 23861918, 2013). "MMP-2 and -9 are soluble MMPs which degrade gelatine and play key roles in tumor angiogenesis, growth and metastasis." (PMID 23799090, 2013). "Recently, screening for MMP in clinical samples identified that some of these including MMP-2 and 9 are upregulated in tumor tissue compared to normal tissue 34,35 and their expression predicts tumor recurrence in several types of cancers 37,38." (PMID 24156018, 2013). "Having demonstrated that osteoblast derived MMP-2 mediated the activation of TGFβ and tumor survival in vitro; we determined the relevance of the mechanism in the in vivo osteolytic tumor-bone microenvironment." (PMID 22238668, 2012). "Decreased bone resorption in the MMP-2 null tumor bearing group compared to wild type controls was further supported by X-ray radiography analysis and by the number of mature multinucleated TRAcP positive bone lining osteoclasts." (PMID 22238668, 2012). "Tumour MMP-2 expression was only detected in 14 of 48 specimens (low expression in 57% and high expression in 43%)." (PMID 23107277, 2012). "It is characterized by orchestrated signaling events involving adhesion molecules and cytokines, and the binding of and activation of MMP-2 promote tumor cell transmigration across the endothelial barrier and thus invade the distant tissue." (PMID 23227342, 2012). "Chlorophyllin and ellagic acid that decrease the expression of MMP-2 and -9 are attractive candidates for inhibiting MMPs and consequent tumor progression." (PMID 22485181, 2012). "The treatment of rapamycin (a mTOR inhibitor) and siRNA-mediated mTOR knockdown inhibit tumor cell invasion as well as the secretions of MMP-2 and uPA." (PMID 23226337, 2012). "MMP-2 degrades the fibrin matrix that surrounds newly formed blood vessels, facilitating endothelial cell penetration of tumor tissue." (PMID 22408395, 2012). "Matrix metalloproteinases (MMPs) play crucial roles in tumor growth and angiogenesis, so we investigated the effect of HB-19 on the expression of MMP-2 and we found that HB-19 downregulates MMP-2 in HUVECs." (PMID 23265284, 2012). "GA-Me effectively inhibited tumor growth, lung metastasis, and tumor invasion through down-regulating matrix metalloproteinase 2/9 (MMP2/9) gene expression." (PMID 23095899, 2012). "The expression of MMP-2 and αvβ3 integrin on the tumor cells was evaluated by immunofluorescence method." (PMID 22848537, 2012). "VEGFA, a growth factor and MMP2, a cellular matrix protein, involved in tumor formation and metastasis are found repressed by Pax6." (PMID 23056534, 2012). "In cancer, MMPs, such as MMP-2 and MT1-MMP, associate with tumor growth, tissue remodeling, tissue invasion, and metastasis." (PMID 23304519, 2012).
tumor (continued). "COUP-TFII staining correlated with ERα, SRC-1, AIB1, Pea3, MMP2, and phospho-Src and was reduced with increased tumor grade." (PMID 22693611, 2012). "In assessing MMP expression in human breast-to-bone metastases and in a mouse model of the osteolytic tumor-bone microenvironment, we found that MMP-2 was largely localized to osteoblasts." (PMID 22238668, 2012). "Approximately more than 59% tumor cells adhered to the culture wells coated with APMA-activated MMP-2 compared with those cells blocked with RGD peptides." (PMID 22848537, 2012). "But in a tumour environment, the final concentration of MMP-2 and -9 would depend on many different cell types, mechanisms and interactions." (PMID 22472880, 2012). "The higher numbers of osteoclasts generated by the MMP-2 null osteoclast precursors was unexpected given that less mature bone resorbing osteoclasts were identified in the tumor-bone microenvironment of the MMP-2 null mice." (PMID 22238668, 2012). "We and others have previously shown that the ablation of host MMP-9 has a minimal impact on tumor/growth or tumor induced osteolysis thus implicating the importance of MMP-2 in the progression of bone metastases." (PMID 22238668, 2012). "Inhibition of miR-21 leads to increasing levels of RECK, a membrane-anchored glycoprotein that inhibits tumor cell invasion by regulating MMP-2, MMP-9 and MT1-MMP." (PMID 22642976, 2012). "MMP-2 expression is also increased in several tumors, which is correlated with the nodal status and tumor stages." (PMID 22778768, 2012). "The observed effect of MMP-2 on tumor growth was confirmed using the unrelated PyMT derived cell line, 17L3C-Luc." (PMID 22238668, 2012). "Here, we present a novel finding that TIMP-1 signaling upregulates MT1-MMP and MMP-2 expression, and potentiates MT1-MMP activation of pro-MMP-2, contributing to tumor cell invasion." (PMID 22701711, 2012). "The effect of snail knockdown to tumor cell invasion, and claudin and MMP2 expression was studied in cell lines." (PMID 23157169, 2012). "The arrival of circulating metastatic tumour cells in the lungs depends on chemokines and adhesion, then extravasation into target tissues depends on proteinases (MMP2, MMP9)." (PMID 23226965, 2012). "In exploring ColIV expression, we also found that tumour expressions of MMP-2 and MMP-9 showed certain variations." (PMID 23107277, 2012). "Our data demonstrate that osteoblast derived MMP-2 regulation of TGFβ bioavailability is critical for promoting tumor cell survival." (PMID 22238668, 2012). "For the first time, these data demonstrate that an osteoblast derived proteinase, MMP-2, can impact tumor survival." (PMID 22238668, 2012). "Previous studies suggested that MMP-9 expression were closely related to tumour angiogenesis than MMP-2." (PMID 23107277, 2012). "αvβ3 integrin-mediated adhesion and migration of the tumor cells were inhibited by a MMP-2 inhibitor." (PMID 22848537, 2012). "A recent report indicated that oesophageal tumors from obese patients express more MMP9 and that co-culture of VIS adipose tissue explants with tumor cells up-regulated MMP2 and MMP9." (PMID 22469146, 2012). "Compelling preclinical studies from diverse laboratories have provided overwhelming support for direct relationship between MMP-2 over expression and tumor invasion/metastasis." (PMID 22962598, 2012). "That the stromal microenvironment plays a critical role in determining tumor cell behavior has been shown in primary tumors, where stromal cells increase MMP-2 expression in tumor cells." (PMID 23227342, 2012). "Consistent with our conclusion that TGFβ was promoting cell survival, we observed significantly higher ratios of phospho AKT to total AKT in the tumor-bone lysates derived from the wild type mice compared to the MMP-2 null mice." (PMID 22238668, 2012).
tumor (continued). "Overall survival was significantly shorter in patients with high tumour and stromal MMP-2 and MMP-9 expression, and tended to be shorter in patients with low ColIV expression." (PMID 23107277, 2012). "We found that conditioned media derived from wild type primary osteoblasts resulted in significantly higher metabolic activity and in a higher number of tumor colonies compared to tumor cells incubated with conditioned media from MMP-2 null osteoblasts." (PMID 22238668, 2012). "Our data also indicate that host MMP-2 contributes to tumor induced osteolysis (μCT, histomorphometry)." (PMID 22238668, 2012). "We found that lysates, normalized for total protein content, derived from the wild type tumor injected tibias had significantly higher levels of active TGFβ compared to the MMP-2 null tumor bone lysates." (PMID 22238668, 2012). "Collectively, these results demonstrated that MMP-2 regulates αvβ3 integrin-dependent tumor cell migration." (PMID 22848537, 2012). "The initial step of tumor cell invasion is characterized by BM breakdown, a process dependent on type IV collagen-degrading enzymes, mainly MMP2 and MMP9." (PMID 23031673, 2012). "Of note, osteoblasts and osteocytes were found to be consistently positive for MMP-2 in human samples and in the control and tumor bearing limbs of the wild type mice but surprisingly, human and murine osteoclasts were largely negative for MMP-2." (PMID 22238668, 2012). "Quantitation of the bioluminescent signal from the PyMT-Luc tumor cells showed a marked decrease in tumor growth rate in MMP-2 null mice compared to wild type controls from day 3 post-injection onwards." (PMID 22238668, 2012). "After the tumor cells were resuspended in an agarose drop, the distribution of MMP-2 and αvβ3 integrin was examined from 1 h to 12 h." (PMID 22848537, 2012). "In longitudinal studies, we found that host MMP-2 significantly contributed to tumor progression in bone by protecting against apoptosis and promoting cancer cell survival (caspase-3; immunohistochemistry)." (PMID 22238668, 2012). "CXCR4 interacts with CXCL12 to promote tumor cell proliferation, induce the expression of MMP2, and increase invasion and metastasis." (PMID 22537906, 2012). "Hagemann and colleagues demonstrated that coculturing TAMs with tumor cells can promote the expression of MMPs, especially MMP2 and MMP9, in TNF-α-dependent manner." (PMID 22778768, 2012). "We showed that MMP-2 was detected on the surface of tumor cells after the cells initially attached to matrix, nevertheless, the signal of co-localization between MMP-2 and αvβ3 integrin was barely detectable." (PMID 22848537, 2012). "We suggest that MMP-2 contributes to tumor survival by controlling the bioavailability of TGFβ via the processing of LTBPs, such as LTBP-3." (PMID 22238668, 2012). "IL-8 is involved in the transcription induction of MMP-2 increasing stromal invasion by tumor cells facilitating angiogenesis and development of metastasis." (PMID 22695075, 2012). "Collectively, αvβ3 integrin-mediated adhesion and migration of tumor cells is regulated, at least in part, by MMP-2 via fibronectin cleavage." (PMID 22848537, 2012). "Early attempts to identify MMPs responsible for mediating tumor invasion focused on soluble MMPs (particularly MMP-2 and MMP-9), and expression of these MMPs correlated with the neoplastic phenotype." (PMID 24213464, 2012). "Active MMP-2 is first recruited to the leading edge of invasive tumor cells and cleaves fibronectin into shorter fibronectin products." (PMID 22848537, 2012). "αvβ3 integrin has been reported to play a critical role in cell adhesion and regulate the migration of tumor cells by promoting MMP-2 activation." (PMID 22848537, 2012). "It would consequently also be interesting to study angiogenesis to better understand the effect of QSOX1 on tumor growth through MMP-2 activity regulation." (PMID 23098186, 2012).